ZNF484 (zinc finger protein 484)
Description:
May be involved in transcriptional regulation.
Synonyms: BA526D8.4; FLJ33884
Tractability: PROTAC: UniProt records ubiquitination sites on it; ubiquitination databases record sites on it.
Gene: Protein-coding gene on chromosome 9 (92,843,171 to 92,878,038, reverse strand). Ensembl gene ENSG00000127081.
Subcellular location: Nucleus
Subcellular location (Human Protein Atlas): Nucleoplasm; Cytosol; Nuclear membrane
Pathways (Reactome):
Gene expression (Transcription): Generic Transcription Pathway
Gene Ontology:
Molecular function: transcription cis-regulatory region binding
Biological process: regulation of transcription by RNA polymerase II; regulation of DNA-templated transcription
Cellular component: nucleus
Genetic constraint (gnomAD): Loss-of-function variants: 12 observed, 13.02 expected, observed/expected ratio (o/e) 0.92, 90% interval 0.59 to 1.49. The synonymous counts are far from expectation, so gnomAD's model fits this gene poorly and the ratio says little. Missense variants: 807 observed, 1,061.2 expected, observed/expected ratio (o/e) 0.76, 90% interval 0.72 to 0.81. Synonymous variants: 289 observed, 354.47 expected, observed/expected ratio (o/e) 0.82, 90% interval 0.74 to 0.9.
Homologues: Orthologues: chimpanzee ZNF484 (99% identical), macaque ZNF484 (96% identical), dog ZNF484 (82% identical), pig ZNF484 (80% identical), rabbit ZNF484 (72% identical), guinea pig ZNF484 (68% identical). Paralogues in human: ZNF585B (48% identical), ZNF41 (47% identical), ZNF585A (46% identical), ZNF175 (41% identical), ZNF658 (41% identical), ZNF33B (39% identical), ZNF182 (38% identical), ZNF605 (38% identical), ZNF300 (37% identical), ZNF630 (35% identical), ZNF470 (35% identical), ZNF568 (35% identical), and 164 more.
Diseases named in the same sentence as ZNF484 in open-access papers:
ZNF484 is named in the same sentence as 4 diseases in open-access papers, as found by Europe PMC text mining. Sharing a sentence is not in itself a finding about the gene and the disease. The quoted sentences say what the papers report.
breast carcinoma (1 paper, 2022). "Our exome wide biomarkers study identified 4 SNPs [SNRK and SNRK-AS1-rs202018563G; BRCA2-rs2227943C; ZNF484-rs199826847C; and DCPS-rs1695739G] as the most significant SNPs among our patients with breast cancer compared to the healthy controls." (PMID 36268271, 2022).
cancer (1 paper, 2021). A tumor composed of atypical neoplastic, often pleomorphic cells that invade other tissues. "Znf484 has been identified as a cancer-associated gene and is involved in hepatic tumorigenesis." (PMID 34233649, 2021).
tumor (1 paper, 2024). "The transcriptional programs regulated by TBX21, ZNF595, FOSL2, ZNF83, ZNF484, IKZF2, and ELK3 were found to be significantly activated in tumor-reactive T cells." (PMID 39243082, 2024).
ZNF484 also shares sentences with these, for which no sentence is quoted: coronary artery disease (1 paper).